IL2 (interleukin 2)
Diseases named in the same sentence as IL2 in open-access papers (continued):
Sharing a sentence is not in itself a finding about the gene and the disease.
tumor (continued). "Given the result that NJB2-IL2 (2 nM affinity to EIIIB) and NJT6-IL2 (no affinity to EIIIB) elicit similar, modest delay in B16F10 tumor outgrowth after i.v. administration, we sought to understand better the design criteria for effective IL-2 immunocytokines." (PMID 36712341, 2022). "Following treatment with 1,4-dihydroxy quininib, significant increases in secretion of IL-13, IL-2 and TNF-α are observed in the primary tumour explants, but not in the UM cell lines." (PMID 36698840, 2022). "It was found that avelumab therapy considerably enhanced cytotoxic activity of NK cells against PD‐L1+ tumor cells of triple‐negative breast cancer (TNBC), and the lytic activity was augmented upon stimulation of NK cells with IL‐2 and IL‐15." (PMID 35301813, 2022). "The trial results showed no reduction in tumor burden and lacked specific localization of CAR T cells to the tumor, followed by toxicities related to IL‐2 activation." (PMID 35844304, 2022). "(f, g) Linear correlation of proCAR oligomeric state vs. IFNγ, IL-2, TNFα, and GM-CSF cytokine production (normalized to CD28TM reference) from 24 hr co-culture with (e) MC57-HER2 and (f) antigen-negative MC57 tumor cells." (PMID 35506657, 2022). "It exhibits a nonspecific immune response to reduce tumor burden by increasing the number of natural killer (NK) cells and CD8+ T cells and by cytokine secretion, including that of interleukin (IL)-2, IL-12, IL-18, and interferon-gamma (INF-γ)." (PMID 36439125, 2022). "T cells are typically long-lived but do not recognize mHsp70 on tumor cells, even after stimulation with TKD/IL-2." (PMID 35720311, 2022). "It is not surprising to see induction of Th1 (IL-2 and IFN-γ) cytokines by unarmed (UA) activated T cells (ATC) co-cultured with tumor cells." (PMID 34290709, 2021). "When MUC1-negative tumour cells (A431)were used as the stimulator, MUC1-specific CAR-T cellsshowed no significant secretion of IL-2 (30 ± 2.82 pg/mL, 1-fold), TNF alpha (8 ± 2.82 pg/mL, 1.7-fold) and IFN-γ (22 ± 2.82 pg/mL, 1.2-fold)." (PMID 32347044, 2021). "The combination of CTLA-4 and PD-1 blockade restored IL-2 production and CD8 T cell expansion in a murine model; however, no additional T cell infiltration into the tumor microenvironment was observed." (PMID 34769156, 2021). "Recently, the fourth generation of CARs carrying a transgenic “payload”' such as IL-2 or IL-15 has been engineered to improve CAR-NK cell proliferation, longevity, and cytotoxicity against antigen-negative tumor cells." (PMID 34215336, 2021). "Other than exerting a relevant cytotoxic activity, both generations of CAR-transduced T cells also produced high and comparable levels of IFN-γ, IL-2, and TNF-α in response to PSMA-expressing tumor targets, but not against PSMA negative control cells." (PMID 34660275, 2021). "Thus, lower level of IFN-γ/IL-2 producing CD4+ T cells of IN_in_r1-immunized mice may have indicated higher levels of CD4+ T cells producing IFN-γ/TNF-α, with the latter, or both events, contributing to a better protection of these mice against tumor challenge." (PMID 34199989, 2021). "CD8+ T-cells lacking PTPN22 demonstrate improved anti-tumour immunity and resistance to suppression mediated by TGF-β, via increased IL-2 expression." (PMID 34960140, 2021). "Previously, we demonstrate that only MACS purified CD3− NK cells (>97%), but not CD3+ T or γ/δ T cells are able to recognize mHsp70+ tumor cells after stimulation with Hsp70 protein or TKD and IL-2." (PMID 34079819, 2021). "Although IL-7/IL-15-treated polyclonal T cells have less differentiation and more anti-tumor efficiency, they either show no significant T cell expansion advantage or a small T cell and CAR T cell expansion compared to IL-2 only-treated cells." (PMID 34217218, 2021).
tumor (continued). "Nevertheless, the effector cytokine production capacity post peptide restimulation in the periphery and at the tumor site was comparable between the SCR and PGC-1α overexpression groups in terms of IFNγ, TNFα, granzyme B, and IL-2 production (data not shown)." (PMID 32055005, 2021). "In order to investigate the anti-tumor effect of NK cells, GBM-induced animals were divided into two trial groups: intracranial and systemic cell therapy models, which received IL-2/HSP70-treated NK cells or nontreated NK cells." (PMID 32218162, 2020). "For the samples with tumor cells (TE-13, A549 or MDA-MB-231) and without T cells, the levels of IL-2 and IFN-γ in cell culture were under the detection limits of the ELISA kits." (PMID 30699956, 2019). "IL15 presents different advantages compared to IL2, including the preferential activation and expansion of memory CD8 and NK cells that promote tumor control with no-Treg expansion." (PMID 31614774, 2019). "Treatment with various cytokines, including IFN-γ, IL-2, IL-4, and IL-6, did not increase VISTA expression in tumour cells." (PMID 30382166, 2019). "Compared to systemic treatment, such as IL-2 infusions, the targeted manipulation of STAT5 activity in tumor-specific CD8 T lymphocytes circumvents the negative stimulation of Tregs, which are also recruited into tumor beds." (PMID 31766350, 2019). "Interleukin-15 (IL-15) is a promising candidate for tumor immunotherapy, since it is a strong activator of both CD8+ T and NK cells and in contrast to IL-2 does not activate regulatory T cells." (PMID 30400835, 2018). "IL-2/anti-CD40 immunotherapy alone did not significantly improve CTL activity in DLN, spleen or tumor of elderly mice." (PMID 30459812, 2018). "Plasma levels of the NK cell-activating cytokines IL-2, IL-15, IL-18, and IL-21 increased substantially within the first 2 days after CY+TBI compared to their plasma levels in 4T1 tumor-bearing mice not subjected to chemo-irradiation." (PMID 27915436, 2017). "ASC-IFNγ engrafted into the tumor stroma inhibited tumor growth and angiogenesis, prevented a systemic increase of Treg, increased CD8+ T cell infiltration (but not IL-2+ cells), and prolonged the survival of mice." (PMID 29181035, 2017). "There were no group differences in tumor protein concentrations of IFN-γ, IL-2, IL-4, IL-5, IL-10, and IL-12p70 (p > 0.05 data not shown)." (PMID 28811490, 2017). "The study reported that EGFR-specific CAR observably potentiated cytotoxicity and induced secretion of IFN-γ and IL-2 in EGFR-positive cell lines and xenograft tumor models, but not in EGFR negative ones." (PMID 28356156, 2017). "Here, the authors fuse IL-2 with an NKDG2 binding domain, and show that it induces IL-2 signalling selectively in NKG2D+ cells, delaying tumour growth in mice without the side effects of conventional IL-2 therapy." (PMID 27650575, 2016). "In IFN-γ and IL-2 ELISPOT assays, splenocytes from immunized mice responded strongly to corresponding mutant 29mer peptides but showed no response to ID8-G7 tumor cells." (PMID 27192170, 2016). "Total number of tumor-infiltrating CD11b+ Gr-1- myeloid cells was increased in IFN-α2, IFN-γ and IL-2 treated groups compared to non-injected control mice." (PMID 26107883, 2015). "TIL155-C1 and TIL155-C2 secreted GM-CSF, IL-2, and IFN-γ but did not secrete IL-4, IL-10, or transforming growth factor (TGF)-β after exposure to 155mel tumor cells." (PMID 25993655, 2015). "Future directions include combining peptide vaccines with chemotherapy and IL-2 (phase II, NCT01795976), and using tumor lysate vaccines in the adjuvant setting with or without chemotherapy (phase I/II, NCT02054104)." (PMID 29546098, 2015). "The co-administration of PAP-GMCSF, -IL2, -IL4 and -IL7 significantly prevented tumor induction and inhibited tumor growth in the PAP-expressing tumors, yet not in the PSA-expressing tumors." (PMID 25632844, 2015).
tumor (continued). "In contrast, r28M as well as CD3 and CD28 alone, did not lead to IL-2 secretion and thus to no activation of PBMC in the absence of tumor cells." (PMID 26469402, 2015). "When stimulated by tumor cells and an anti-CD3 antibody, Vγ1 T cells express IFN-γ and GM-CSF, but not IL-1β, TNF-α, IL-12, IL-2, IL-4, IL-10, or TGF-β." (PMID 25538706, 2014). "Other cytokines analyzed (GM-CSF, IL-2, IL-4, IL-10, IL-12 (p70), IL-13, IL-17, VEGF and TNFα) were below detection level of the assay, or did not exhibit any significant changes upon tumor growth or Delta24-RGD treatment (results not shown)." (PMID 24866126, 2014). "In WT mice receiving Fab anti-CD200R, no tumor cells are detectable following immunotherapy, and CD4+ cells produced increased TNFα/IL-2/IFNγ on stimulation with EMT6 in vitro." (PMID 25409195, 2014). "Cytokines, such as interleukin-2 (IL-2), interferon-α (IFN-α), and tumor necrosis factor-α (TNF-α) have been used non-specifically to stimulate an anti-tumor response." (PMID 24860566, 2014). "We have previously demonstrated that IL-2 based immunotherapy, in combination with CD40 agonist, results in synergistic anti-tumor effects which are CD8+ T-cell dependent but not antigen restricted and." (PMID 25119341, 2014). "For example, NK cells preactivated with IL-12/IL-15/IL-18 rather than IL-2 proliferated rapidly, produced high level of interferon γ (IFN γ), and induced pronounced tumor regression." (PMID 24741604, 2014). "Originally termed T Cell Growth Factor (TCGF), IL-2 was demonstrated in early studies to endow human lymphocytes with ability to selectively kill tumor but not healthy control cells." (PMID 24884532, 2014). "Induced by IL-2, spleen lymphocytes signal to LAK cells, which can lyse not only self tumor cells but also isotype entity tumor cells." (PMID 24206544, 2013). "Human peripheral blood lymphocytes upon stimulation with IL-2 (a lymphokine known back then) turn NK and CD8+ T cells into nonspecific killer cells that lyse tumor cells in vitro." (PMID 22899945, 2012). "Multiple murine studies have demonstrated that systemic administration of IL-2, with or without BCG, can significantly decrease tumor size, suppress tumor growth, and improve mean survival." (PMID 22778725, 2012). "In contrast, IL-2, IL-7 and IL-15 induced p-STAT5 in tumor-infiltrating T cells were not different from normal T cells." (PMID 23072591, 2012). "The resulting mixture of tumor cells and stromal cells, including TIL, was cultured in the presence of high-dose IL-2 but without the addition of any exogenous peptide, antigen or mitogen." (PMID 23110239, 2012). "The lack of IL-2 production by both CD8+ and CD4+ T cells in these experiments is also consistent with an impaired anti-tumor response." (PMID 21203522, 2010). "According to our work, Th1 cytokines (IL-2 and IFN-γ) and Th2 cytokines (such as IL-4 and IL-5) are not the major cytokines produced by tumours." (PMID 17261184, 2007). "The implications of these findings are that, while tumor cell lysis by chimeric T cells is independent of CD28, IL-2 secretion will be lacking under these circumstances." (PMID 16507098, 2006). "A total of 34 patients treated with low dose IL-2, IFN-α with or without histamine were evaluable for consecutive tumour biopsies." (PMID 14760375, 2004). "IL-2 treatment may promote cell-based immunity against PDAC, not only by stimulating tumor-specific T-lymphocytes but also by enhancing dendritic cell infiltration." (PMID 39773310, 2025). "Furthermore, studies such as the IL-2 trial incorporate tumor burden as part of their criteria; however, other metastatic CRC trials do not include tumor volume as a selection factor." (PMID 40507337, 2025). "However, neither the IL‐2 and IFNγ levels nor the surface expression of CD69 of T cells activated by I3A‐treated tumor cells was changed by autophagy inhibitors." (PMID 40583248, 2025).
tumor (continued). "We hypothesize that the gain on efficacy would exceed the toxicity cost, especially because the most burdensome part of traditional TIL therapy is the high-dose IL-2 treatment, which should not be needed with IL-2 produced by TILT-123 at tumor site." (PMID 40107242, 2025). "Again, analysis on tumor tissue (injected and non-injected) could provide knowledge on virus-induced changes and the viral production of TNF and IL-2." (PMID 40107242, 2025). "We first detected the mitochondrial mass by Mitotracker staining of NK cells under the presence of tumor cells, which mimic the TME, and found that the mitochondrial mass significantly decreased in BBζ treated with IL-2 rather than Neo-2/15, when co-cultured with tumor cells." (PMID 40025022, 2025). "Additionally, this study did not assess the effects of IL-2 or its receptor blockade, nor did it examine CD4+ T cell depletion using in vivo tumor models." (PMID 40343532, 2025). "Furthermore, whereas peripheral CD8+ T cells express little to no CD25, tumor-infiltrating CD8+ T cells greatly upregulate CD25 on antigen recognition, enabling them to effectively compete with Tregs for IL-2." (PMID 40789741, 2025). "Furthermore, the TOX expression in CD8+ effector T cells was induced by Treg-mediated IL-2/STAT5 activation, while CD8+ tissue-resident T cells showed no corresponding changes in tumor samples." (PMID 40698080, 2025). "However, no CR or tumor regression were shown in these two mouse models and the activity of SAR444245 was not compared to WT IL-2 or PEG-IL-2." (PMID 39114660, 2024). "Similarly, EphA2-TEA-VV directed T-cells towards cancer cells, activated T-cells through secretion of IFN-γ, IL-2, and binding to CD3, and induced bystander killing of noninfected tumor cells." (PMID 38558795, 2024). "In particular, our investigation into its role in immune escape mechanisms uncovered a significant positive correlation with immune-suppressive cytokines (TGF-β, IL-10, and IL-1β) and a negative correlation with anti-tumor cytokines (IFN-γ, IL-2, and TNF-α) in metastatic lung cancer." (PMID 38951802, 2024). "Interestingly, even treated with a high dose (120 μg) of IL-2–blocking Abs, KO mice lacking tumor-infiltrating Tregs displayed a relatively high frequency (~79%) of CD44hiCD62lo CD8+ TILs, comparable to that in WT mice without IL-2 blockade." (PMID 38787791, 2024). "Importantly, ablation of PGE2 signalling and consequently reconstitution of IL-2 signalling sufficed to achieve clonal TIL expansion and their effector differentiation within tumours that was not accompanied while preserving TCF1+ stem-like TILs." (PMID 38658748, 2024). "The tumor-nonspecific OVA SLP and the tumor-specific altered-self SLP Gp10017 were both adjuvanted with imiquimod and supplemented with IL-2, and the lymphocytic choriomeningitis virus (LCMV)-derived tumor-nonspecific Gp34 SLP18 was supplemented with TLR9 agonist CpG as adjuvant." (PMID 38167722, 2024). "Therefore, compared with CTRL-not-α-mIL2, CD8+ T-cell cis-targeted IL2 shows a superior ability to increase the numbers and functionality of intratumoral antigen-specific CD8+ T cells in multiple tumor models." (PMID 38563906, 2024). "Although initially IL2 was routinely used alone in CAR-T cell expansion procedures, it was later demonstrated to promote CAR-T cell terminal effector and exhausted phenotypes without persistent in vivo tumor killing effects." (PMID 38225288, 2024). "Notably, this next-generation IL-2 drug preferentially binds CD122 (and shows no CD25 affinity) on immune cells and acts as a powerful switch for activating and proliferating tumor-killing effector NK and T lymphocytes to fight cancer." (PMID 37483629, 2023). "Finally, ex vivo culture of CAR T cells in IL-7 and IL-15 rather than traditional IL-2 is also known to favour the central memory (TCM) phenotype and increase tumour control." (PMID 37291434, 2023).
tumor (continued). "Two separate groups have described this mutant IL-2 “orthokine” pair and demonstrated its effectiveness in combination with suboptimal doses of CAR-T cells, leading to CAR-T expansion, tumor reduction, and persistence without the need for repeated CAR-T infusions." (PMID 38090585, 2023). "This latter aspect could be particularly relevant in the context of the solid tumors, as IL-2-primed NK cells undergo AICD following interaction with endothelial cells, with a possible negative impact on extravasation and tumor infiltration." (PMID 37388731, 2023). "Two days after treatment initiation, interferon gamma (IFNG, best known as IFNγ) and interleukin 2 (IL2), which are produced upon CAR T cell activation, became detectable above background in ALL-bearing (but not tumor-naïve) mice receiving CAR T cells (but not in mice treated otherwise)." (PMID 37142568, 2023). "While in vitro tumour lysis of PD-L1+ tumour cells was not improved by the addition of an IFP to the CAR T cells, their cytokine secretion in terms of IFN-γ, IL-2 and Granzyme B concentration in the coculture supernatant was higher than control T cells that were transduced with CAR only." (PMID 37400680, 2023). "Indeed, a recent study showed that IL2 and BLIMP1 induced cytotoxic function in tumor-specific CD4 T cells, and that this occurred independent of TBET-mediated induction of a Th1 polarization state." (PMID 37654482, 2023). "Nevertheless, by BLT we could not identify an additional effect of IL-2 on EGFR CAR T cell and BDCA-2 CAR T cell expansion at the tumor, since an overall higher signal in the whole mouse ROI was detected in IL-2-treated mice." (PMID 35836798, 2022). "The primary in silico sink for locally injected IL-2 fusion proteins was clearance from circulation and not uptake by T cells, in part due to the low initial abundance of IL-2R+ cells in our poorly inflamed B16F10 tumor model." (PMID 35013154, 2022). "Indeed, we find that certain synthetic IL-2 circuits drive highly efficient CAR T cell infiltration and tumor control in immune-excluded solid tumor models, without concomitant systemic or off-target toxicity." (PMID 36520915, 2022). "However, treatment with several cytokines, including IFN-γ, IL-2, IL-4, and IL-6, did not raise VISTA expression in tumor cells." (PMID 34728682, 2021). "This is because BiTEs mediate target cell killing mainly via (non-tumor) antigen-experienced T cells that differentiate to effector memory T cells after activation and these cells can be reactivated without costimulatory signals such as CD28 and IL-2." (PMID 34885176, 2021). "5T4 CAR‐T cells could elicit lytic cytotoxicity to target tumor cells in the 5T4‐dependent manner and secreted cytotoxic cytokines, including IFN‐γ, IL‐2, and GM‐CSF when compared with nontransduced (NT) T cells in vitro." (PMID 34766126, 2020). "Importantly, this leads to the recruitment of T cells and production of IFN-γ, IL-2, and TNF-α, which leads to tumor cell kill, but not necessarily through tumor specific mechanisms." (PMID 32858811, 2020). "Moreover, the IL-2-dependent non-leukemic T-cell lines infected with HTLV-1 acquired IL-2-independency and turned into tumor-producing cancer cells as with the ATL cell lines." (PMID 32210945, 2020). "Finally, the antitumor activities of naïve nontreated and IL-2/HSP70-treated NK cells were evaluated and compared by MRI, showing effectiveness of treated NK cells manifested by tumor shrinkage, both after intracranial and systemic injection." (PMID 32218162, 2020). "Further studies have demonstrated that mHsp70 on tumor cells, even in the absence of HSP-chaperoned peptides, can be recognized by natural killer (NK) cells, particularly after ex vivo stimulation with Hsp70 peptide TKD and low-dose IL-2." (PMID 32443761, 2020).